LRRK2 (leucine rich repeat kinase 2)
Diseases named in the same sentence as LRRK2 in open-access papers (continued):
Sharing a sentence is not in itself a finding about the gene and the disease.
Crohn disease (continued). "There are numerous genes that are involved in autophagy, including ATG16L1, NDP52, IRGM, and LRRK2 that have been found to be mutated in Crohn’s Disease patients; a number of these mutations also manifest with multiple clinical presentations." (PMID 29743550, 2018). "Mutations in the leucine-rich repeat kinase 2 (LRRK2) gene are found in familial and idiopathic cases of Parkinson's disease (PD), but are also associated with immune-related disorders, notably Crohn's disease and leprosy." (PMID 28202666, 2017). "A role of LRRK2 in immune regulation is suggested by meta-GWAS studies identifying LRRK2 as a susceptibility locus in Crohn’s disease (CD) and leprosy." (PMID 27830463, 2017). "In this study, we found that LRRK2, encoded by a gene implicated in Crohn’s disease, leprosy and familial Parkinson’s disease, modulates the strength of Nod1/2-Rip2 signaling by enhancing Rip2 phosphorylation." (PMID 27830463, 2017). "LRRK2 is also associated with the inflammatory bowel disorder Crohn’s disease, hinting that it is involved in regulating intestinal inflammation." (PMID 27461410, 2016). "In support of a crucial role of this protein in the immune system, genome-wide association studies identified Lrrk2 as one of the susceptibility genes for leprosy and Crohn’s disease, two illnesses with a significant inflammatory component." (PMID 26646749, 2015). "Intriguingly, the LRRK2 locus been implicated in Crohn's disease and susceptibility to leprosy, providing a genetic link to immune disease and recent studies have highlighted a potential role in microglial response within the brain." (PMID 23938341, 2013). "Association studies have identified several signals at the LRRK2 locus for Parkinson's disease (PD), Crohn's disease (CD) and leprosy." (PMID 23967090, 2013). "Curiously, GWAS findings have demonstrated that a certain SNP in LRRK2 is associated with inflammatory bowel diseases such as Crohn's disease and ulcerative colitis." (PMID 22550610, 2012). "Intriguing recent studies also demonstrate that mutations in LRRK2 are significant risk factors in Crohn’s disease, an inflammatory disease of the bowel." (PMID 22723946, 2012). "Leucine rich repeat kinase 2 (LRRK2) is associated with Crohn’s disease through a GWAS meta-analysis but a nearby gene (MUC19 which encodes a mucin) is as likely to be the gene of interest." (PMID 21994779, 2011). "N551K was reported to confer protection to both PD and Crohn’s disease, and an overexpression study showed a mild but statistically significant negative impact of N551K on MLi-2-induced association between LRRK2 and microtubules." (PMID 41171629, 2025). "Furthermore, variants of the LRRK2 gene have been associated with increased susceptibility to both PD and Crohn’s disease." (PMID 40399949, 2025). "Our approaches allowed us to confidently measure LRRK2 expression and activity in different types of immune cells, including T cells, monocytes and macrophages that have been implicated in infection control and in Crohn’s disease." (PMID 40394349, 2025). "The LRRK2 genetic connection to both PD and Crohn’s disease lends support to this association." (PMID 39338563, 2024). "In addition, LRRK2 is associated with several inflammatory or infectious diseases, including Crohn’s disease, systemic lupus erythematosus, and leprosy." (PMID 38227290, 2024). "Furthermore, Paneth cell deficiencies are common in Crohn's disease patients, and LRRK2 is essential for maintaining Paneth cell function." (PMID 39883213, 2024). "Additionally, several genome-wide association studies revealed that mutations in leucine-rich repeat kinase 2 (LRRK2) that are one of the greatest genetic contributors to PD are also linked to increased incidence of Crohn’s Disease (CD), a form of IBD." (PMID 36824371, 2023). "LRRK2 is also a major susceptibility gene for Crohn’s disease and increased gut inflammations." (PMID 38196993, 2023).
Crohn disease (continued). "Mutations in leucine-rich repeat kinase 2 (LRRK2) are the most common monogenic genetic causes of both familial and sporadic PD, and they are also present in other inflammatory diseases such as Crohn’s disease and leprosy." (PMID 35456966, 2022). "Another variant in the LRRK2 gene, p.N2081D, was described as a risk factor for Crohn’s disease." (PMID 35054514, 2022). "We expressed various LRRK2 variants that possessed the N551K R1398H variant on its own or in the presence of additional variants that are associated with increased risk for PD or Crohn’s disease." (PMID 34145320, 2021). "The LRRK2 locus is implicated in immune-related disorders, such as Crohn’s disease and leprosy." (PMID 33672296, 2021). "Interestingly GWAS studies revealed an association between Crohn’s disease or leprosy and LRRK2 mutations, suggesting a possible link between LRRK2 and inflammatory diseases." (PMID 33210214, 2021). "In addition to PD, previous GWAS have also identified LRRK2 in a susceptible locus for Crohn’s disease and leprosy, both of which are immune-related disorders." (PMID 32256311, 2020). "This pattern of expression may be put into relation with the finding that genetic association studies have found LRRK2 to be a risk factor for inflammatory bowel disease (Crohn’s disease, CD)." (PMID 33013290, 2020). "The M2397T polymorphism in LRRK2 is genetically associated with sporadic Crohn’s disease (CD)." (PMID 32180132, 2020). "Notably, LRRK2 is genetically implicated in the pathogenesis of IBDs, including Crohn’s disease and ulcerative colitis." (PMID 32714591, 2018). "In addition, mutations in the LRRK2 gene were found to be associated with Crohn’s disease, an inflammatory bowel disease." (PMID 26067490, 2015). "The CARD15 gene known to be associated with Crohn's disease is over-represented in patients with PD; vice versa, the Leucine-rich repeat kinase 2 (LRRK2) gene, a causative PD mutation, was recently identified as a major susceptibility gene for Crohn’s disease by genome-wide association studies." (PMID 25775153, 2015). "Research on susceptibility genes identified by GWAS indicates that some autoimmune diseases such as Crohn's disease may share mutations on the same gene LRRK2, which has exemplified the significance of immune system in the pathogenesis of PD." (PMID 25050341, 2014). "Intriguingly, GWAS have implicated LRRK2 in the pathogenesis of Crohn's disease (CD) and leprosy." (PMID 23967090, 2013). "Finally, in the context of the role that LRRK2 plays in human disease, it is noteworthy that LRRK2 has been implicated in a number of human disorders, including Crohn’s disease, Cancer and Leprosy in addition to PD." (PMID 24211199, 2013). "Interestingly, two recent GWAS found that common LRRK2 variants are also associated with Crohn’s disease (CD), an inflammatory bowel disease, and leprosy, a chronic infectious disease caused by Mycobacterium leprae." (PMID 22594666, 2012). "Furthermore, LRRK2 variants have been associated with Crohn's disease (CD), an inflammatory bowel disease." (PMID 23251830, 2012). "It was also reported that B-lymphoblastoid cell lines carrying LRRK2 mutations display impaired growth and that LRRK2 might be associated with increased susceptibility to Crohn's disease." (PMID 21738687, 2011). "Therefore, gut inflammation and higher LRRK2 levels in Crohn’s disease may be biomarkers of increased risk for idiopathic PD and could even represent tractable therapeutic targets." (PMID 40399949, 2025). "LRRK2 is highly expressed in both monocytes and microglia, the residential immune cells or the macrophage cells of the brain, and mutations of LRRK2 also underlie susceptibility to immune diseases, including leprosy and Crohn’s disease, highlighting a potential immunologic function." (PMID 34568343, 2021).
Crohn disease (continued). "Interestingly, LRRK2-mediated transcriptional alterations are also associated with Crohn’s disease, a type of inflammatory bowel disease, and LRRK2 alleles contributing to both PD and Crohn’s disease have been identified." (PMID 29977190, 2018). "Besides PD, LRRK2 has also been associated with susceptibility to Crohn's disease and leprosy." (PMID 23028814, 2012). "The genomic locus that encodes the Leucine-rich repeat kinase 2 (LRRK2) gene is highly pleiotropic, being associated with both Parkinson's disease (PD) and Crohn's disease (CD)." (PMID 41648127, 2026). "In a second and independent study, we cultured PBMC from patients with Crohn’s disease with Needle-Tox alone in the absence and presence of the LRRK2-kinase inhibitors, LRRK2-IN-1 and CZC54252.HCl, as indicated in Methods." (PMID 41246319, 2025). "Mutations in the LRRK2 gene were identified as a potential risk factor for inflammatory bowel disease (IBD) and Crohn’s disease." (PMID 40867920, 2025). "Previous studies have implicated LRRK2 polymorphisms in autoinflammatory diseases including inflammatory bowel disease (IBD), Crohn’s disease, and tuberculosis, indicating a significant connection to immune functions." (PMID 41146185, 2025). "This study develops tools to measure LRRK2 activity and expression in immune cells relevant to Crohn’s disease, revealing inflammatory and tissue-specific regulation." (PMID 40394349, 2025). "As research progresses, more and more autophagy-related Crohn's disease susceptibility genes have been identified, such as IRGM, ULK1, LRRK2, TLR4, etc.." (PMID 39883213, 2024). "Correspondingly, associations between LRRK2 carrier status and other immune conditions, including Inflammatory Bowel Disease (IBD)/Crohn’s Disease, have been raised." (PMID 39175765, 2024). "Another predicted GOF variant, p.Asn2081Asp in LRRK2, reported as benign in ClinVar, but has been previously shown to have a GOF effect and associated with Crohn’s disease." (PMID 38037155, 2023). "Reports have linked NOD2 to LRRK2-dependent intestinal homeostasis and RIPK2 phosphorylation, and LRRK2 polymorphisms are also associated with Crohn’s disease and leprosy susceptibility, indicating a common genetic network at play." (PMID 37262021, 2023). "This multifunctional aspect of LRRK2 contributes to its involvement in different human diseases, including cancer, leprosy, Crohn's disease and other inflammatory diseases." (PMID 37698513, 2023). "The N551K-R1398H-K1423K LRRK2 haplotype is associated with reduced risk for developing PD, REM behavior sleep disorder, and Crohn’s disease, with a combined odds ratio for PD of approximately 0.8230,33–35,49." (PMID 34145320, 2021). "Variants in LRRK2 within the ROC, COR, kinase, and WD40 domains have been linked to increased risk for PD or Crohn’s disease and have been reported to lead to increased Rab10 phosphorylation." (PMID 34145320, 2021). "Finally, we showed that missense variants in LRRK2 associated with reduced risk for PD and Crohn’s disease lead to lower levels of Rab10 phosphorylation, suggesting that these variants may lower disease risk by reducing the activity of the LRRK2 signaling pathway." (PMID 34145320, 2021). "Studies of LRRK2 KO mice have shown that LRRK2 in Paneth cells is involved in the lysosome sorting process to protect from enteric infection, pointing to a potential pathological mechanism for Crohn’s disease involving LRRK2 in Paneth cells." (PMID 33013290, 2020). "Genetic variants such as the leucine-rich repeat kinase 2 gene (LRRK2), which regulates inflammatory responses, are common in Crohn's disease, a chronic inflammatory intestinal disease, and familial as well as sporadic PD." (PMID 31534664, 2019). "Recently, Hui and colleagues reported that variations in the LRRK2 locus tend to have similar effects on the odds ratio of Crohn’s disease and PD." (PMID 32714591, 2018).
Crohn disease (continued). "For example, increased LRRK2 expression has been observed in inflamed colonic tissues from patients with Crohn's disease." (PMID 28099919, 2017). "Coherently, analysis of inflammed colonic tissue from Crohn’s disease patients revealed increased levels of LRRK2 expression." (PMID 26646749, 2015). "The leucine-rich repeat kinase 2 (LRRK2), identified as a major susceptibility gene for Crohn’s disease, was reported to act as a negative regulator of NFAT1/c2-induced cytokine responses." (PMID 24479879, 2014). "Furthering interest in LRRK2, PARK8 has subsequently been associated with cancer, leprosy, and Crohn’s disease." (PMID 23754980, 2013). "Knock out rodent models for LRRK2 have likewise revealed important insights into LRRK2 biology – providing evidence of a link to autophagy and to Crohn's disease." (PMID 23938341, 2013). "One study strengthened the argument that LRRK2 is a Crohn’s disease gene by demonstrating that this gene is regulated by IFNγ and expressed in immune cells in the mucosa of patients." (PMID 21994779, 2011). "Expression of LRRK2 by dendritic cells and macrophages in Crohn's disease patients has recently been reported." (PMID 21738687, 2011). "Expressed across various cellular subsets, including myeloid cells, B cells, T cells, microglial cells and epithelial cells, LRRK2 upregulation in the lamina propria of intestinal biopsies from Crohn’s disease(CD) patients underscores its pivotal role in intestinal inflammation." (PMID 38607004, 2024). "In addition to PD, LRRK2 has been reported to be associated with inflammatory bowel diseases (IBD) which is composed of two major subtypes, Crohn’s disease and ulcerative colitis, based on genome-wide association studies." (PMID 37904222, 2023). "Studies have revealed that SNPs in LRRK2 gene have been related to Crohn’s disease." (PMID 33658398, 2021). "LRRK2 is critical for the propagation of Crohn's disease, leprosy, and neuronal toxicity." (PMID 34239490, 2021). "Furthermore, polymorphisms in the LRRK2 gene have been linked to inflammatory diseases such as leprosy and the IBD, Crohn’s disease (CD), highlighting a critical role of LRRK2 in inflammation." (PMID 32508566, 2020). "Here we asked whether LRRK2 modifies inflammatory signaling and how this modification might contribute to PD and Crohn's disease." (PMID 32111741, 2020). "LRRK2, the gene encoding the multidomain kinase Leucine-Rich Repeat Kinase 2 (LRRK2), has been linked to familial and sporadic forms of Parkinson’s disease (PD), as well as cancer, leprosy and Crohn’s disease, establishing it as a target for discovery therapeutics." (PMID 30055128, 2018). "Moreover, it was recently reported that LRRK2 and Rab2a regulate Paneth cell function, which is compromised in Crohn’s disease." (PMID 26824392, 2016). "Recently, both LRRK2 and LRG have been linked to Crohn’s disease (CD)." (PMID 24058569, 2013). "It is not clear at the LRRK2/MUC19 locus which is the key associated gene with Crohn's disease, although a recent study suggests that LRRK2 is the more likely to be truly disease-associated." (PMID 21152001, 2010). "Leucine-rich repeat kinase 2 (LRRK2), a risk gene of PD, is highly expressed in microglia, monocytes and other immune cells, and has been reported to be associated with an increasing risk of Crohn’s disease, an inflammatory bowel disease and other autoimmune diseases." (PMID 38590523, 2024). "LRRK2 variants have also been tested in neurodegenerative diseases such as PSP, AD, dementia with Lewy bodies (DLB), MSA, and essential tremor; specific LRRK2 variants have also been linked to inflammatory diseases such as Crohn’s disease and infectious diseases such as leprosy." (PMID 33494262, 2021). "However, the abnormal function of LRRK2, GBA, SNCA, PARK2, PARK6, and PARK7 genes has been linked to alteration in innate and adaptive immune responses in cancer, stroke, diabetes, male infertility, Crohn's disease, and infectious diseases." (PMID 34239490, 2021).
Crohn disease (continued). "LRRK2 and DJ-1 were also found to be expressed in different populations of human peripheral blood mononuclear cells (PBMCs) and may contribute to autoimmune diseases such as Crohn's disease, leprosy, and multiple sclerosis." (PMID 25050341, 2014). "We tested whether genes associated with Crohn's disease are also associated with ankylosing spondylitis and confirmed that the two diseases share associations at chromosome 1q32 near KIF21B, STAT3, IL12B, CDKAL1, LRRK2/MUC19, and chromosome 13q14." (PMID 21152001, 2010). "This study of genes associated with Crohn's disease has identified definite genome-wide significant association with AS of SNPs at chromosome 1q32 near KIF21B, and experiment-wise association at five other novel-AS loci including STAT3, IL12B, CDKAL1, LRRK2/MUC19, and at chr13q14." (PMID 21152001, 2010). "In the present study, we explored the relation of LRRK2-kinase phosphorylation of the NLRC4 inflammasome to NLRC4 inflammasome function in normal humans and mice, as well as in patients with Crohn’s disease (CD)." (PMID 41246319, 2025). "CASM-dependent LRRK2 activation may also be relevant for Crohn’s disease, where human genetics has established roles for both ATG16L1 and LRRK2, and our data now place these genes into a common cellular pathway." (PMID 39812709, 2025). "The autophagy pathway requires many of the same proteins utilized by other membrane trafficking events, and understanding how LRRK2 and VAMP3 regulate autophagy or mucosal immunity appears important regardless of their significance in Crohn’s disease." (PMID 21994779, 2011).